HELLS (helicase, lymphoid specific)
Diseases named in the same sentence as HELLS in open-access papers (continued):
Sharing a sentence is not in itself a finding about the gene and the disease.
infection (2 papers, 2010 to 2021). The state of being infected such as from the introduction of a foreign agent such as serum, vaccine, antigenic substance or organism. "Proteins in this category that exhibited decreases during infection included the SWI/SNF protein family member Lymphoid-specific helicase (HELLS/SMARCA6/LSH) and the ATP-dependent DNA helicase Q4 (RECQL4)." (PMID 34463575, 2021). "To explore further the potential association of HELLS/SMARCA6 and/or SMARCAD1 with viral genomes, we assessed the intracellular localization of these proteins during mock, Ad5 WT, and AdΔE4 infections using immunofluorescence (IF) microscopy." (PMID 34463575, 2021). "The expression of the four cell proliferation/survival genes (C11ORF82, PGR, SOX11 and HELLS) are significantly reduced when C. burnetii's protein synthesis is inhibited during infection of THP-1 cells." (PMID 20854687, 2010). "The immunoblot data also show that HELLS/SMARCA6, RECQL4, SQSTM1/p62, and DCAF1 each exhibit decreased protein abundances during Ad5 WT infection, consistent with the WCP data." (PMID 34463575, 2021). "The decreases in abundance observed for HELLS/SMARCA6, RECQL4, SQSTM1/p62, and DCAF1 during Ad5 WT infection were mitigated during AdΔE4 infection, suggesting that manipulation of these proteins is dependent on one or more E4 gene products." (PMID 34463575, 2021). "The WCP data suggest that each of the selected proteins (HELLS/SMARCA6, RECQL4, SQSTM1, and DCAF1) are decreased during Ad5 WT infection, with distinct abundance change profiles." (PMID 34463575, 2021). "Additionally, neddylation inhibition induces a partial mitigation of decrease in protein abundance of HELLS/SMARCA6 and SQSTM1/p62 during Ad5 WT infection." (PMID 34463575, 2021). "HELLS/SMARCA6 exhibits diffuse nuclear localization without obvious colocalization with DBP during infection with Ad5 WT or AdΔE4 viruses (data not shown)." (PMID 34463575, 2021).
HELLS also shares sentences with these, for which no sentence is quoted: gastric cancer (3 papers); genetic disorder (3); leukemia (3); head and neck cancer (2); ovarian carcinoma (2); squamous cell carcinoma (2); Alpha-thalassemia (1); and Facial anomalies (1); endocervical adenocarcinoma (1); gastric adenocarcinoma (1); gastrointestinal infections (1); idiopathic pulmonary fibrosis (1); invasive ductal carcinoma (1); nasopharyngeal tumor (1); osteoporosis (1); ovarian tumours (1); pancreatitis (1); sarcoma (1).